CGAS (cyclic GMP-AMP synthase)
Diseases named in the same sentence as CGAS in open-access papers (continued):
Sharing a sentence is not in itself a finding about the gene and the disease.
cancer (continued). "However, while cGAS-STING inhibitors may protect against inflammation-driven diseases of aging, they may promote acute infection and cancer due to prolonged suppression of the neuroinflammatory response." (PMID 35741054, 2022). "Although the cGAS-STING pathway may have apoptosis-promoting effect by inducing type I interferon signaling, recent studies have shown that promotion of cancer progression and metastasis is the dominant effect of cGAS-STING pathway activation in cancer cells." (PMID 35468978, 2022). "This DSBs-induced cGAS-STING activation and inflammatory response is dependent on cell cycle progression through mitosis, which is an important mechanism to explain the genotoxic cancer therapy-induced delayed on sets inflammatory response in contrast to the acute DNA-damage response." (PMID 34374004, 2022). "The cGAS-STING axis activation by therapeutic agents that induce DNA damage, such as certain chemotherapies, continues to be reported, highlighting the importance of the interplay of this signaling pathway and the DNA damage response in cancer immunity/immunotherapy." (PMID 36559204, 2022). "The cGAS-STING axis is composed of cyclic GMP-AMP synthase (cGAS) and cyclic GMP-AMP receptor stimulator of interferon genes (STING) and responds to pathogens or damaged DNA as a crucial immune axis in microbial infection, chronic inflammation, cancer progression and organ degeneration." (PMID 35145201, 2022). "Additional epigenetic mechanisms active in HPV-positive cancers, leading to suppression of the cGAS-STING pathway, have also been suggested, involving E7-induced upregulation of SUV39H1 methyltransferase and downregulation of histone demethylases KDM5B important for cGAS-STING expression." (PMID 34696321, 2021). "Altogether, these observations demonstrate that the cGAS-STING pathway might play an important role in maintaining chromosome integrity through senescence induction, and that in this context this pathway also contributes to SASP instauration in cancer cells." (PMID 34079557, 2021). "As STING is widely expressed in various cell types and can regulate different pathways of programmed cell death, a deeper understanding of the cGAS–STING signaling pathway may bring a new dawn to treat infections, chronic inflammatory diseases, and even cancer." (PMID 34483930, 2021). "Our current finding that eribulin rapidly and specifically activates cGAS-STING through mtDNA release in both TNBC and immune cells including those that are terminally differentiated is significant particularly in solid tumors that have a much lower mitotic index than cancer cells in culture." (PMID 34312217, 2021). "In recent years, extensive research has demonstrated that SASP is activated by the cGAS-STING pathway, and its proinflammatory role has been demonstrated to be crucial for the occurrence of autoinflammatory disorders, age-related diseases and even cancer progression." (PMID 34123836, 2021). "Accumulating evidence suggests key proteins in the cGAS-STING signaling pathway as potential drug targets, and relevant agonists could fundamentally improve the efficacy of current cancer treatments, including surgery, chemotherapy, radiotherapy, and immunotherapy." (PMID 34483930, 2021). "In addition to the cGAS-STING pathway, ICD, release of DAMPs and cytokines can enhance adjuvanticity, elicit migration of pro-anti-cancer immune subpopulation, decrease immunosuppressive cells, alter TME and tilt immune response to cancer cell killing." (PMID 34579759, 2021). "Furthermore, although most studies on STING have shown that STING modulates senescence via the canonical cGAS/STING pathway, in this study, we demonstrated an unconventional mechanism of STING-mediated senescence, independent of cGAS, in cancer cells." (PMID 33558529, 2021).
cancer (continued). "Though, the cGAS-STING signalling axis has been identified recently that may require more investigations, various chemotherapeutic as well as radiotherapeutic approaches rely heavily on this signalling pathway to eradicate cancer." (PMID 33922087, 2021). "Notably, cGAS-STING can directly activate the indoleamine 2,3-dioxygenase (IDO) on cancer cells." (PMID 34072037, 2021). "On the other hand, cGAS-STING signaling pathway activation in cancer cells also recruits supportive immune cells to clear carcinoma directly and non spontaneously, such as enhancing the sensitivity of cancer cells to immune attack by natural killer (NK) cells and CTLs." (PMID 34483930, 2021). "Interestingly, the expression of CD47 on cancer cells not only provides “do not eat me” signals, but also has been shown to interfere with antigen cross-presentation by cDCs by interrupting cGAS-STING activation." (PMID 34290401, 2021). "How frequently this non-canonical STING signaling is engaged in human cancers remains to be determined, but the fact that it can be engaged independently of cGAS suggests that it could be relatively common." (PMID 35087822, 2021). "Although the oncogene-like role of cGAS is contradictory to the positive role of cGAS in cell death the complexity might be context-dependent like the reported differential roles of the cGAS–STING pathway in cancers." (PMID 33105828, 2020). "Since mtDNA stress can trigger ISG expression via the cGAS-STING pathway in the cytosol, we hypothesized that mitochondrial Lon–ROS-induced mtDNA release into the cytosol triggers IFN signaling via a cGAS-STING-TBK1 pathway in cancer." (PMID 33268351, 2020). "Altogether, these data demonstrate that cGAS–STING signaling in MSCs are activated by IR and drives the production of CCL5, which can remodel the lung microenvironment via recruiting macrophages that are essential for the colonization of cancer cells in the lung." (PMID 32382015, 2020). "Although cGAS and STING are poised to respond to pathogens, increasing evidence supports their critical role in a number of “sterile” physiologic and pathologic conditions, including cancer, heart disease, diabetes, neurodegenerative disease, lupus as well as normal aging/cellular senescence." (PMID 33552072, 2020). "Apart from the intrinsic cGAS-STING activation in malignancies, metastasis could also be induced in a cancer cell non-autonomous manner." (PMID 32571374, 2020). "Altogether, these results indicate that paclitaxel treatment recruits cGAS/STING activation in response to unstable nuclear membrane of induced micronuclei and that this induces a secretory phenotype which promotes BCL-xL-dependent apoptotic priming in untreated cancer cells." (PMID 31937780, 2020). "Given that the cGAS-STING pathway can be beneficial and harmful in terms of antitumor immunity, the future direction of therapeutic strategies involving the cGAS-STING pathway should consider the efficiency and safety concerns of the treatment in different stages and type of cancers." (PMID 33633744, 2020). "A part of the answer to this apparent paradox might be that the activation of the cGAS-STING pathway in cancers does not always lead to downstream immune signaling." (PMID 31658669, 2019). "Apart from recognizing foreign DNA, cGAS-STING pathway could sense self-DNA derived from damaged and dying cells, which contributes to sterile inflammation in the context of autoimmune diseases and anti-cancer immunity." (PMID 30935414, 2019). "Independent of enhanced anti-cancer immunity, cGAS-STING pathway could directly activate senescence and apoptosis signaling pathways in cancer cells." (PMID 30935414, 2019). "Even though the cGAS-STING signaling axis has only recently been identified and many aspects of this pathway need further investigation, many of the ‘classic’ chemotherapeutic and radiotherapeutic approaches to eradicate cancer heavily rely on this signaling route." (PMID 31658669, 2019).
cancer (continued). "In addition, more details are emerging about the cGAS-STING pathway that might argue for more extensive research into the exact function of its components; specifically in the setting of human cancer." (PMID 31114634, 2019). "Whichever the underlying mechanism might be, one key conclusion is that tumors tend to block IFN signaling preferentially downstream of cGAS and STING expression, which suggests that cGAS and STING might have IFN-independent functions that are beneficial for cancer cells." (PMID 31658669, 2019). "Here, recent understanding of the role of cGAS/STING pathway in cancer and its therapeutic modulation has been reviewed, with an aim to emphasize the point that a better understanding and artificial tunability is required for optimal targeting of this pathway as a potential cancer immune therapy." (PMID 29156566, 2017). "However, cancer cells may evade immune surveillance by silencing cytosolic DNA sensing pathways, leading to reduced or absent expression of cGAS and STING." (PMID 40830678, 2026). "However, it remains unknown whether class A ODNs can activate the cGAS pathways in other cell types, such as fibroblastic reticular cells (FRC), which play critical roles in modulating the immune environments during inflammatory diseases and cancer." (PMID 40337520, 2025). "Notably, many cancer treatment strategies, such as chemotherapy, radiotherapy, targeted therapy, and immunotherapy, highly rely on the activation of IFN-I signaling pathways, especially the cyclic GMP-AMP synthase (cGAS)-stimulator of interferon genes (STING) pathway." (PMID 39034318, 2024). "In addition, the cGAS-STING pathway activated by CIN/aneuploidy may be involved in the antitumor adaptive immune response, which has been found to provoke a CD8+ T cell response against cancer." (PMID 36003402, 2022). "However, cGAS-STING-mediated SASP or autophagy have not been fully elucidated in cancer cells." (PMID 34123836, 2021). "However, cGAS-mediated autophagy has not been elucidated in cancer cells." (PMID 34123836, 2021). "Given the delayed cGAS recruitment (>24 h) after DNA damage, our observations with SV40T-expressing cells may be related to their cell cycle progression through mitosis, a phenomenon recently shown to promote cytoplasmic DNA leaking and cGAS activation in cancer cells." (PMID 28974621, 2017). "As for other genes involved in dsDNA/dsRNA/ssRNA sensing like CGAS, RIG-I, MAVS, DDX41, and IFI16, whose expression in either cancer cells or other cell types, were not significantly impacted by redox status of any cell types." (PMID 41378285, 2025). "The cGAS-STING signaling pathway exhibits extensive expression across immune cells, non-immune cells, and cancer cells." (PMID 40621423, 2025). "In the transwell system, T-DXd failed to induce cGAS-STING pathway activation or upregulation of CD86 and HLA-DR in TDDCs where direct physical interaction between cancer cells and DCs was prevented." (PMID 39449023, 2024). "Although activation of the cGAS–STING signaling pathway plays a negative role in RA pathogenesis, its role in cancer remains clear." (PMID 39125448, 2024). "It was indicated that the expression of cGAS and STING is usually inhibited in most cancer types, rather than being upregulated, especially when tumors are well-developed." (PMID 36769349, 2023). "In triple negative breast cancer cells with CIN, the depletion of cGAS–STING resulted in a reduction in IL-6 production and impaired cancer cell survival." (PMID 37534795, 2023). "Indeed, despite having high amount of dsDNA in their cytoplasm, type I IFN is hardly produced in cancer cells at the basal level without other stimulations, suggesting that cGAS-STING pathway may be somehow perverted in these cells as a mechanism of escape from immune sensing." (PMID 37180110, 2023). "The cGAS-STING pathway suppression has been observed in colorectal carcinoma, melanoma, and cancer cells lacking telomerase." (PMID 37834184, 2023).
cancer (continued). "Unlike cancer cells, stromal cells consistently displayed strong STING protein expression without evidence of cGAS+ micronuclei." (PMID 37612508, 2023). "The extensive works carried out to understand the correlation between expression of cGAS/STING and cancer will not be discussed in this review but recently presented in." (PMID 33708225, 2021). "The cGAS-STING pathway activation has been shown to activate canonical and – in cancer cells – non-canonical nuclear factor kB (NF-kB), mitogen-activated protein (MAP) kinases, and signal transducer and activator of transcription (STAT) transcription factors." (PMID 34386500, 2021). "The ability of human cGAS to discriminate long dsDNA strands from shorter dsDNA may contribute to the specific sensing and recognition of the “danger DNA” of pathogens, necrotic cells or cancer cells rather than irrelevant shorter dsDNA, thereby enhancing the immunity against them specifically." (PMID 32411126, 2020). "Communication between cancer cells and the vasculature can modulate infiltration of immune cells and regulate the composition of the TME, though the role of cGAS-STING signaling in this process has not been characterized." (PMID 33013881, 2020). "This would thus prevent type I INF activation without deregulating cGAS or STING expression levels, and thus be another mechanism for cancer cells with a CIN phenotype to circumvent immune surveillance." (PMID 31658669, 2019). "cGAS-STING activity can also be triggered in a cell non-autonomous manner, for instance through uptake of cancer cells by antigen presenting cells (dendritic cells and macrophages)." (PMID 31658669, 2019). "However, recent studies have challenged this conventional view, revealing that cGAMP can be exported by cancer cells in a paracrine manner, activating STING in neighboring cells independent of cGAS." (PMID 40770563, 2026). "Unlike cancer cells or the HAP1 cells, the cGAS-STING pathway is intact in BJ-5ta." (PMID 41509453, 2026). "Interestingly, the class A ODN-induced cGAS disappearance is only observed in FRC, but not in bone marrow-derived macrophages, bone marrow-derived dendritic cells, or murine and human cancer cell lines." (PMID 40337520, 2025). "The expression levels of cGAS and STING were significantly lower in MOC2 cells compared to MOC1 cells, suggesting that the observed differences in protein levels originate from the cancer cells rather than the stromal cells." (PMID 40282455, 2025). "Thus, it is not surprising that genetic and epigenetic suppression of cGAS and STING has been observed in several cancer types." (PMID 39621308, 2024). "This pathway plays an established role in immune surveillance; however, cancer cells commonly dampen STING activity while retaining cGAS’s sentinel function, suggesting that cGAS may perform additional stealthy roles independent of STING." (PMID 39080411, 2024). "Thus, self and non-self-sources of cytosolic dsDNA can trigger cGAS/STING signaling in a very large variety of cell-types including immune cells, endothelial cells, fibroblasts, epithelial and cancer cells." (PMID 37180110, 2023). "However, for the purpose of this review, it should be mentioned that is has, so far, not been possible to study anti-cancer drugs targeting AIM2, Sox2 or cGAS-STING pathway exclusively in neutrophils." (PMID 37483598, 2023). "The cGAS–STING pathway is widely expressed in immune, non-immune, and cancer cells." (PMID 37686127, 2023). "Given the fact that cGAS-STING is an important biomarker for cancer diagnosis and targeting the cGAS-STING signaling pathway represents a new therapeutic strategy, we evaluated the score of cGAS-STING signal in different tumors and their corresponding normal tissues." (PMID 35983076, 2022).
cancer (continued). "cGAS and STING co-expressing PDAC cases showed favorable survival, with many cytotoxic CD8 + T cell infiltrations from the stromal component adjacent to the cancer cells toward cancer cells, but not in cGAS-STING signaling defected PDAC cases." (PMID 35773436, 2022). "Nevertheless, most cGAS-STING signaling pathway agonists have not yet encountered cancer-promoting effects, as only a few doses of treatment can lead to a burst production of type I IFN, which activates the anti-cancer immune system." (PMID 34483930, 2021). "Furthermore, regardless of its partner cGAS, STING can localize to the inner nuclear membrane in breast cancer tumor samples and promote cancer cell survival by resistance to DNA-damaging agents through interacting with DNA-PK." (PMID 34970273, 2021). "However, it should be noted that activation of the cGAS-STING pathway does not always exert an antitumor effect and can be a double-edged sword in cancer treatment." (PMID 34445736, 2021). "In conclusion, we ascertained that most human cancer cells respond to cytosolic RNA through the RIG-I–MAVS–IRF3 signaling pathway, while the cGAS–STING pathway is activated despite the absence of IFN-β secretion in cGAS and STING intact human cancer cell lines." (PMID 33490069, 2020). "Using a mouse model, Bakhoum and coworkers showed that highly genetically unstable cancer cells with high chromosomal instability and an activated cGAS/STING pathway are more prone to form metastases than cancer cells with a more stable genome that do not activate the cGAS/STING pathway." (PMID 35008251, 2021). "In summary, the co-enrichment of ESCRT-III and RPA/cGAS at a subset of micronuclei and the absence of RPA/cGAS enrichment upon CHMP7 depletion, point to a non-canonical (VPS4-independent) function for ESCRT-III in maintaining a pool of cytosolic DNA in cancer cells." (PMID 30988276, 2019). "Indeed, several correlative pan-cancer studies have related the degree of aneuploidy and CIN to increased markers of immune evasion and a decreased cytotoxic immune infiltrate, suggesting a role for CIN, albeit not necessarily CIN-driven cGAS–STING, in driving immunosuppression." (PMID 36876871, 2023).